FOXP3 (forkhead box P3)
Diseases named in the same sentence as FOXP3 in open-access papers (continued):
Sharing a sentence is not in itself a finding about the gene and the disease.
tumor (continued). "We found that all the unresponsive tumors showed higher levels of Foxp3, CTLA4, and Tim3 than responsive tumor tissues." (PMID 39128094, 2024). "IF analysis of 4T1 tumor sections revealed an increase in CD8+ T cells and NK1.1+ cells, coupled with a decrease in FOXP3+ T cell infiltration following the combination treatment." (PMID 38971872, 2024). "The five variables selected were Tumor region CD8+, Tumor region PD-L1+, Tumor region CD8+PD-L1+, Tumor region Foxp3+, and Lymphocyte Nuclei, respectively." (PMID 38887237, 2024). "Nevertheless, the correlation found between several immune cell populations, and in particular between FoxP3+ and CTLA-4+ cells, suggests a potential role of immune cells in canine splenic HSA where mechanisms of tumor evasion are activated." (PMID 38672372, 2024). "Two weeks after treatment with SBRT alone, the results showed increased tumor densities of CD3+ T cells, FoxP3+ Tregs, and CD204+ macrophages, along with increased expression of genes associated with immunosuppression." (PMID 39195816, 2024). "Dianzani C and others found that ICOS-Fc treatment inhibited tumor cell migration to the lungs in mice, increasing IL-17A and RAR-related orphan receptor C (RORc) expression while reducing IL-10 and Foxp3 expression." (PMID 39104717, 2024). "Using TSA-associated multiplex immunofluorescence, we analyzed the proportion of CD8+ T lymphocytes, CD20+ B lymphocytes, FoxP3+ T regulatory lymphocytes, and CD163+ macrophages in tumor samples prior to immunotargeted therapy." (PMID 38612743, 2024). "Scutellaria barbata can modulate the infiltration of Treg and Th17 cells in the tumor microenvironment, reducing the number of CD4+,CD25+,Foxp3+,Treg cells and Th17 cells in tumor tissues." (PMID 39274982, 2024). "Meanwhile, high PD-L1+ lymphocyte infiltration in islets was predominantly found in tumours with high levels of IL-17A+CD4+ T cells in islets and Foxp3+CD4+ T cells in islets and stroma (p = 0.032, p = 0.009 and p = 0.034, respectively)." (PMID 39409156, 2024). "The ratios of FoxP3+ and CD45RO+ cells over the CD3+ cells in the tumor area as well as the ratios of FoxP3+ over the CD45RO+ cells in the tumor area were significantly associated with clinical outcomes." (PMID 38887294, 2024). "In this study, we found FoxP3 expression in tumor tissue was significantly lower than that in para-tumor tissue, while CD133 was significantly higher in tumor tissue compared to para-tumor tissue." (PMID 39073490, 2024). "Eventually there was significant correlation between PD-L1 IC and the number of tumour-infiltrating CD4+ T cells (r = 0.279, p = 0.018), as well as Foxp3+CD4+ T cells (r = 0.251, p = 0.034)." (PMID 38541208, 2024). "An eleven-marker panel (CD3, CD4, CD8, FOXP3, CD68, arginase-1, CD33, HLA-DR, pan-keratin (PanCK), PD-1, and PD-L1) was used to study the tumor and immune cell compositions." (PMID 38898200, 2024). "Our results showed that tumor‐infiltrating CD8+ T cells, the CD8/FOXP3 ratio, and ICMs were significantly higher in patients receiving NAC." (PMID 38455493, 2024). "To achieve this, we correlated the expression of GAL‐3 in frozen tumor samples with the infiltration of FOXP3+, CD4+, and CD8+ lymphocytes as well as the expression of these markers in FPEE from tumor and tumor‐near stroma compartment." (PMID 37567864, 2024). "To our knowledge, we are the first who evaluated PD-L1+ lymphocyte distribution in tumour tissue in the context of the TME (CD4+ T cells, Foxp3+CD4+ T cells, IL17A+CD4+ T cells, CD8+ T cells, M1 and M2 macrophages)." (PMID 39409156, 2024). "Conversely, IL-33 signaling encourages the proliferation of suppressive CD4+ Foxp3+ GATA3+ Treg cells, especially in tumor-specific environments high in IL-33." (PMID 40236667, 2024). "Within the tumor microenvironment, LAG-3 expression is markedly upregulated, particularly in advanced melanoma, where it acts on tumor-infiltrating CD4CD25 high FoxP3 Treg subsets." (PMID 39743998, 2024).
tumor (continued). "Relationship of TGFβ/FoxP3, TGFβ/VEGF and TGFβ/CD31groups with clinicopathological variables of tumor aggressiveness." (PMID 39165025, 2024). "In the pre-treatment tissues, more stromal CD3 + FoxP3 + Tregs and CD86+/CD163 + macrophages were observed in patients with residual tumor existed in the resected lymph nodes (pN1), compared with patients with pCR." (PMID 38802821, 2024). "By reducing infiltrated TAMs in PDAC with clodronate liposomes, Yang et al136 found that CD8+ T cell infiltration increased, the number of CD4+ Foxp3+ Tregs decreased, and effector CD8+ T cells were spatially brought closer to tumor cells." (PMID 40458305, 2024). "Multiplex IHC staining of five different immune cell markers (CD8, CD68, FOXP3, PD1, and PD-L1) confirmed the validity of inferring tumor immune microenvironment features from a multiomics dataset." (PMID 39482530, 2024). "Analysis revealed a close relationship between the expression of CD163, Foxp3, and ICOS in CRC tissues and tumor TNM staging." (PMID 39104717, 2024). "PDI-1 decreased the abundance of infiltrating FoxP3+ CD4+ T cells and consequently reduced the growth of the tumor." (PMID 38674427, 2024). "The spatial immune architecture of a subset of tumors (n=30) was evaluated using multiplex immunohistochemistry (mIHC) which allowed us to determine the tumor infiltration status of CD3+, CD8+, FoxP3+, CD163+ and Ki67+ cells." (PMID 38638445, 2024). "This was associated with an increase in activated PD-1+ tumor-infiltrating Tregs and suppression of CD4+Foxp3− and CD8+ T cells in tumor tissues." (PMID 38672681, 2024). "These include TH1 (T-bet), TH2 (GATA-3), Treg (FOXP3), and TH17 (RORgt), As a result, T-bet+ cell IHC has occasionally been used as a readout for TH1 cells in tumor tissue." (PMID 39712007, 2024). "Immunofluorescence staining of tumour tissue showed that TNFR2 and CCR8 were coexpressed in FOXP3+ Tregs." (PMID 37935468, 2024). "In the syngeneic PC model, IL30-targeting immunoliposomes downregulated NFKB1 expression and prevented intratumoral influx of CD11b+Gr-1+MDCs, Foxp3+Tregs, and NKp46+RORγt+ILC3, and prolonged host survival by inhibiting tumor progression." (PMID 39232121, 2024). "In particular, those patients with high FOXP3 expression levels in the tumor compartment and low CD4 levels in the tumor or in the stroma had higher levels of LGALS3 in tumor." (PMID 37567864, 2024). "The two panels (listed in Method) included a tumor-related marker (PANCK) for tumor and stroma recognition, two T-cell lineage markers (CD8 and FoxP3), and two TLS-related markers (CD20 and CD23)." (PMID 39313575, 2024). "Tumor-infiltrating lymphocytes, particularly CD8+ cytotoxic T cells, and the balance between CD8+ and CD4+/forkhead box P3+ regulatory T cells in the tumor microenvironment have emerged as critical factors." (PMID 38541669, 2024). "The first panel was designed to identify cytokeratin+ (CK+) tumor/epithelial cells, CD3+ T cells, CD3+Foxp3+ regulatory T cells (Tregs), CD20+ B cells, and CD117+CK− mast cells." (PMID 39510069, 2024). "Multiplex immunohistochemistry and multispectral imaging was used to evaluate tumour infiltration of cytotoxic T cells (CD8+), Th1 cells (T-bet+), T regulatory cells (FoxP3+), B cells (CD20+), and macrophages (CD68+) in a cohort of 257 CRC patients." (PMID 38040818, 2024). "To determine whether enhanced anti-tumor immunity in Opnfl/flFoxp3YFP-Cre mice is Treg intrinsic, we transferred purified CD3+CD4+ and CD3+CD8+ effector T cells (T regulatory cells were depleted as we sorted Foxp3-YFP-) into Rag2−/− hosts along with Opn-deficient Tregs or wild-type controls." (PMID 39272810, 2024). "The current observations suggest that the balance between CD25+ or CD25+FOXP3+CD45RA− cells and CD8+ cells, corresponding to promoting or inhibiting effect on tumor angiogenesis, affect tumor chemosensitivity leading to prognostic significance." (PMID 39232704, 2024).
tumor (continued). "Regulatory T cells (Tregs, CD4_cluster2) with FOXP3, CTLA4, ICOS, and BATF expression were also abundant, which has been demonstrated as tumor-specific alterations in the tissue microenvironment." (PMID 39514276, 2024). "Here, using multiple tumour models and biopsies from cancer patients, we report that α-SMA+ CAFs can form immunological synapses with Foxp3+ regulatory T cells (Tregs) in tumours." (PMID 38862534, 2024). "The findings from qRT-PCR and immunohistochemistry (IHC) analyses revealed a significant upregulation of both FOXP3 mRNA and protein levels in GBM tissues compared to non-tumor brain tissues." (PMID 38561331, 2024). "The ratio and density of the CD8T_exhausted cells (CD8A+PD1+), Treg cells (FOXP3+), Treg_suppressive cells (FOXP3+PD1+), and malignant cells (CK+) in both total area and tumour area decreased in the OT sample." (PMID 39415331, 2024). "Strikingly, dual ICB abrogated tumor growth in FibΔZeb1 mice combined with a more robust increase in CD8+ T cells, ablation of FOXP3+ cells, and reduced PD-L1 expression (D and EV5E)." (PMID 38937629, 2024). "It is constitutively expressed on FOXP3+ Tregs, resulting in elevated levels of immunoregulatory cytokines IL-10 and TGF-β, which suppress tumor-specific T-cell responses." (PMID 39877377, 2024). "Regulatory T cells (Tregs), CD4+IL2RA+FOXP3+, were found mixed with CD4 T cells from tumor samples (tCD4)." (PMID 39516494, 2024). "While Foxp3+CD4+ T cells, also known as Tregs, distribution in tumour tissue alone has been extensively studied, the results remain controversial." (PMID 39409156, 2024). "The AUC values, in descending order, were as follows: Tumor region CD8+PD-L1+ (95.8333%), Tumor region PD-L1 +(91.6667%), Tumor region CD8 +(93.0556%), Tumor region Foxp3+ (79.1667%), Tumor region CD163+ (77.7778%), and Tumor region CD3+Foxp3+ (77.4306%)." (PMID 38887237, 2024). "Thirty ASACs with known tumor size, metastatic status, and clinical stage were immunolabeled for Iba1 (macrophages), CD20 (B cells), CD3 (T cells), and Foxp3 (regulatory T cells)." (PMID 39765600, 2024). "As expected, the vast majority of immune cell markers, such as CD163, S100A8, CD3, and FOXP3, showed higher expression levels in the TME compartment, while Ki-67, which was detected in proliferative tumor cells, was upregulated in tumor cells." (PMID 38951801, 2024). "This dual modulatory effect was mirrored in tumor-infiltrating NKT cells, where a decrease in the percentage of PD-1+, FoxP3+, IL-10+, and KLRG1 MFI+ expression was accompanied by an upregulated expression of the activating receptors NKp46 and FasL." (PMID 38892058, 2024). "They found a higher density of CD8+ cytotoxic T cells, FoxP3− CD4+ helper T cells, and FoxP3+ CD4+ Tregs at the tumor margin." (PMID 39683528, 2024). "These TIM-3(+) CD4 T cells in tumor tissues produce lower levels of Th1 cytokines and express higher levels of CD25, Foxp3, CTLA-4, and GITR." (PMID 39206199, 2024). "Tumor-derived exosomes activate the cGAS-STING pathway in naive lymphocytes, activating Foxp3, STAT5, and SMAD3 to promote the transformation of naive CD4+ T cells into Treg cells, thereby mediating immunosuppression." (PMID 39464890, 2024). "This pattern was also observed in the tumor microenvironment, where there was a noticeable rise in T cells expressing NKp46, FasL, IL-17, and STAT3, along with a decrease in PD-1+ and FoxP3+ T cells." (PMID 38892058, 2024). "Similar to the homeostatic conditions, tumor-bearing CD11c:DTA mice showed a reduced proportion of CD4+Foxp3+ Treg cells and an enhanced proportion of CD4+Foxp3+RORγt+ Treg cells in TdLNs and Spl as compared with tumor-bearing WT mice." (PMID 39206204, 2024). "The levels of CD8+ T cells and FOXP3+ Tregs in the TME significantly affect the survival of tumor cells, suggesting that the high expression of MEG3 plays an important role in tumor immune escape." (PMID 39263534, 2024).
tumor (continued). "It was also found that there exists a subset of T cells expressing CD4+CD25-CD69+Foxp3-LAP+, which inhibits T cell proliferation and promotes tumor immune escape by secreting TGF-β." (PMID 39703499, 2024). "Immunohistochemical characterization identified these cells as CD8+, CD4+, CD20+, FOXP3+, CD163+, or CD68+ cells, and the density of each cell type in the tumor-immune microenvironment (TIME) was quantified." (PMID 39272861, 2024). "We performed a multiplex mIHC staining on tissue sections from 18 samples in the study cohort, and simultaneous detection of CD4/CD8+ lymphocytes, CK+ tumor cells, PD1+ cells, Foxp3+ cells, and TCF1+ cells in the TME by Inform 2.6." (PMID 39009684, 2024). "Even before overt tumor outgrowth, significantly increased CD8+ and FOXP3+ cell infiltration was observed (Fig. EV4F–H), suggesting that the acute inflammation triggers a compensatory regulation of the immune microenvironment upon Zeb1 loss in fibroblasts." (PMID 38937629, 2024). "The remaining number of tumours split into quite equal parts for “desert” and “excluded” immune phenotypes, except for Foxp3+CD4+ and M1 tumours, where “desert” was more common than the “excluded” immune phenotype." (PMID 39409156, 2024). "Subsequently, a significant elevation in Tregs cells (CD4+ FOXP3+) and a reduction in effector cells (CD8+/CD19+) in the tumor tissues of NSCLC clinical specimens from 40 patients undergoing combined chemotherapy and immunotherapy was observed." (PMID 38981044, 2024). "Tumors with the highest CD47 expression also had decreased numbers of FOXP3+ T-cells, resulting in a favorable cytotoxic to regulatory T-cell ratio post NACT in favor of anti-tumor immunity." (PMID 39138571, 2024). "Immunohistochemistry (IHC) was used to assess the infiltration of CD3+, FoxP3+ and CD45RO+ cells in the tumor area, tumor margin and adjacent normal-like epithelium of a series of 98 PCa samples with long clinical follow-up." (PMID 38887294, 2024). "In contrast, the other group (immune-cold) showed elevated levels of the NE signal CD56, as well as increased expression of the Treg markers FOXP3 and CD127, highlighting a resistant or exhausted tumor microenvironment." (PMID 39231924, 2024). "Immunophenotyping of residual tumors showed that TKI treatment with either sorafenib or lenvatinib led to reduced tumor-infiltrating CD8+ T cells and increased immunosuppressive CD4+Foxp3+ regulatory T cells (Treg)." (PMID 38310091, 2024). "Research shows that suppressive CD4+ Foxp3+ GATA3+ Treg cells proliferate in response to ST2/IL-33 signaling, both in vivo and in vitro, which aids in immunosuppression and tumor immune evasion." (PMID 40236667, 2024). "Five clusters of PanCK positive tumor cells were identified: PanCK positive, PanCK/PD-L1 double positive, PanCK/PD-L1/CD33 triple positive, PanCK/CD33/FOXP3 triple positive, and PanCK/CD68/CD33/PD-L1/FOXP3 positive." (PMID 38898200, 2024). "Immune checkpoint molecules (ICMs; PD‐1, PD‐L1, CTLA‐4, LAG3), tumor‐infiltrating lymphocytes (TILs; CD8, FOXP3), and other related proteins were evaluated by immunohistochemistry." (PMID 38455493, 2024). "OESO_0120 had low intra-tumoural CD8+ cells in both pre- and post-tumour tissues, along with low intra-tumoural CD163+ and FoxP3+ cells in pre- tumour tissue, consistent with a likely immune desert phenotype." (PMID 37965317, 2023). "There is evidence that Foxp3+ Treg cells increase in the peripheral blood of HCC patients and infiltrate into tumours, becoming an independent prognostic factor for overall survival." (PMID 37471521, 2023). "Tumor-infiltrating lymphocytes (TILs) comprise different subtypes of lymphocytes with high immunogenicity against tumor cells CD4+, CD8+, CD20+ and FoxP3+ TILs." (PMID 37190214, 2023). "FOXP3 knockdown with AZD8701, an antisense oligonucleotide, has exhibited a significant tumor growth reduction in an in vivo model." (PMID 36816749, 2023).
tumor (continued). "Phenotypes (Tumor - CK+, Cytotoxic - CD3+CD8+, Tregs - CD3+FOXP3+, Macrophages - CD68+, Other- T cells – CD3+CD8-) were characterized using the lineage and functional markers." (PMID 38179056, 2023). "Tumors with an infiltrative pattern of invasion had a higher density of PD-1+ cells in the tumor epithelium (p = 0.03), and higher CD8−/FOXP3+ cells in the stroma (p = 0.01)." (PMID 36368129, 2023). "Elevated levels of TGF-β can inhibit anti-tumour immunity by activating SMADs and NFAT to induce the expression of FOXP3 in CD4+ T cells, which can promote their differentiation to a Treg phenotype." (PMID 38259489, 2023). "The specific function of forkhead box P3 (FOXP3)/HAT1 axis is described in BC; it is able to modulate regulatory T-cells (Tregs) infiltration in the tumor microenvironment." (PMID 37048148, 2023). "Similar to our observations in mouse, CCR8+ FOXP3− Tconv cells expressed high levels of CD25 and were significantly enriched in tumor tissue compared to healthy adjacent tissue and blood from the same patients." (PMID 38100544, 2023). "The presence of tumor-infiltrating lymphocytes (TILs) expressing CD3, CD8, CD68, PD-L1 (detected by antibody SP142) and FOXP3 at primary and metastatic LN sites was quantified." (PMID 36892732, 2023). "CD8+ TILs demonstrate cytotoxicity toward tumor cells, while FoxP3+ TILs and CD163+ TAMs suppress antitumor immunity, contributing to tumor progression." (PMID 36764954, 2023). "This study found that only CD204+ cells, corresponding with macrophages, were higher in tumor areas of BM compared to the primary tumor, whereas CD4+ T cells, CD8+ T cells, and CD+ FOXP3 T cells were higher in the primary tumor." (PMID 37876939, 2023). "Reportedly, PTEN downregulation in the HCC mouse model reduced CD8+T cells infiltration in tumor tissue, along with increasing immunosuppressive Foxp3+CD4+CD25+Tregs and upregulating PD-L1 expression on tumor cells." (PMID 37007125, 2023). "We found a small population of tumor-infiltrating CD8 (~10% of total T cells on average) together with CD4 helper and regulatory CD4+/FoxP3+ T cells (<50% of total CD4+ T cells) in Renca tumors." (PMID 38259453, 2023). "Previous studies have demonstrated that increased CD4+CD25+FoxP3+ Treg cells in RCC were related to worse outcomes, and the FoxP3+ tumor cells have been detected in the tumor–normal tissue borders." (PMID 37569676, 2023). "CD4+ TILs exhibited heterogeneous expression of both T-bet and FoxP3 in established tumours (D14 & D21), while CD4+ TILs in early-stage tumours (D7) were mainly FoxP3-T-bet- (75% of total CD4+ TILs)." (PMID 37153625, 2023). "To further understand the role of Foxp3 in BRCA cell invasion, we evaluated the activity of matrix metalloproteases (MMPs) required to promote tumor invasion and metastasis." (PMID 37766222, 2023). "Aiming to discover further potential treatment approaches, we investigated the role of MR3 expression in the CRC tumor immune microenvironment by immunohistochemical analysis for a selection of promising immunomarkers: CD8, FOXP3, IL17, TIA-1, CD16 and OX40." (PMID 37175905, 2023). "For nCT patients, a previous study also reported increased intra-tumour CD8+ T cell density, but decreased FoxP3+ cell density post therapy." (PMID 37965317, 2023). "In the tumor microenvironment (TME), Foxp3 activation in Tregs generates an exhausting microenvironment, inducing TGF-β and IL-10 expression or downregulating IL-2." (PMID 37766222, 2023). "There is also evidence that anti-Gal-9 antibodies promote the expansion of cytotoxic CD8+ cells in a mamary tumor mouse model, reducing a population of tumor-enabling Treg cells (CD4+, Foxp3+, CD25+)." (PMID 38022609, 2023). "A higher FoxP3 expression level in tumor tissues than in benign tissues was also validated in the GSE781 datasets, which included nine tumor and eight benign tissues." (PMID 37569676, 2023).